DUSP13B (dual specificity phosphatase 13B )
Gene: Protein-coding gene on chromosome 10 (75,094,432 to 75,109,206, reverse strand). Ensembl gene ENSG00000293542.
Diseases named in the same sentence as DUSP13B in open-access papers:
DUSP13B is named in the same sentence as 4 diseases in open-access papers, as found by Europe PMC text mining. Sharing a sentence is not in itself a finding about the gene and the disease. The quoted sentences say what the papers report.
lung adenocarcinoma (1 paper, 2025). A carcinoma that arises from the lung and is characterized by the presence of malignant glandular epithelial cells. "Conversely, the mRNA level of DUSP13B was downregulated in lung adenocarcinoma tissues with EGFR mutations (P = 0.025)." (PMID 39721017, 2025). "We also analyzed the association between SHH, DUSP13B, and p‐STAT3 proteins in lung adenocarcinoma tissues and found that p‐STAT3 was significantly positively correlated with SHH but negatively correlated with DUSP13B." (PMID 39721017, 2025). "In addition, we conducted IHC staining on 108 lung adenocarcinoma tissues and assessed the association between the protein levels of SHH, DUSP13B, p‐STAT3, and EGFR gene mutation status." (PMID 39721017, 2025). "The association among expression of SHH, DUSP13B, and p‐STAT3 proteins in lung adenocarcinoma." (PMID 39721017, 2025). "In lung adenocarcinoma, p‐STAT3 is positively correlated with SHH but negatively correlated with DUSP13B." (PMID 39721017, 2025). "We then utilized the GEPIA2 online platform to examine the correlation among the mRNA levels of SHH, GLI1, DUSP13B, and STAT3 in lung adenocarcinoma tissues from the TCGA dataset." (PMID 39721017, 2025).
lung carcinoma (1 paper, 2025). "To accurately determine the expression level of the SHH/DUSP13B/p‐STAT3 axis in osimertinib‐resistant lung cancer tissues, we collected 10 pairs of clinical lung cancer tissue specimens before and after osimertinib resistance and conducted IHC staining." (PMID 39721017, 2025). "Moreover, our study highlights the clinical relevance of these findings, demonstrating the increased expression of SHH, p‐STAT3, and GLI1 proteins in postosimertinib‐resistant lung cancer tissues, along with decreased DUSP13B expression." (PMID 39721017, 2025). "Furthermore, DUSP13B protein was mainly expressed in the cytoplasm, with lower expression levels observed in postosimertinib‐resistant lung cancer tissues." (PMID 39721017, 2025).
cancer (1 paper, 2025). A tumor composed of atypical neoplastic, often pleomorphic cells that invade other tissues. "This further suggests that DUSP13B may have a negative regulatory relationship with p‐STAT3, and further verification of this finding is needed in other types of cancer tissues in future studies." (PMID 39721017, 2025).
DUSP13B also shares sentences with these, for which no sentence is quoted: tumor (1 paper).